APP (amyloid beta precursor protein)
Diseases named in the same sentence as APP in open-access papers (continued):
Sharing a sentence is not in itself a finding about the gene and the disease.
amyloid (continued). "According to previous studies, DNLAs are not only effective in attenuating amyloid pathogenesis by decreasing APP and Aβ but can also attenuate tau pathology." (PMID 38539620, 2024). "The progressive human amyloid pathology in APP+/− transgenic (Tg) rats was examined and compared to APPxhTau rats at 12, 20 and 24 months of age (M)." (PMID 39707506, 2024). "Bi-genic mice, such as the PSAPP strain, express mutations to both APP and PS1 (APP/PS1), whilst the most extensive amyloid model to date is the 5xFAD mouse, which contains five familial AD mutations." (PMID 38892408, 2024). "Oral administration of EGb761 at 50 mg/kg/day for 6 months also improves cognition in APP/PS1 mice by inhibiting amyloid plaque deposition and downregulating pro-inflammatory cytokines." (PMID 38892521, 2024). "To assess the effect of CAR signaling on macrophage phenotype using a more physiologically relevant target, we cultured control macrophages and CAR-Ms on amyloid-laden brain slices from aged APP/PS1 mice." (PMID 38516884, 2024). "These exosomes efficiently transported bioactive components to the cortex and hippocampus and led to a reduction in amyloid plaque deposition, beta-amyloid levels and inflammation in transgenic mice (human amyloid precursor protein(APP)/presenilin 1 (PS1))." (PMID 38474125, 2024). "The obtained bispecific diabody, after fusion with the low-density lipoprotein receptor-binding domain of the apolipoprotein B for enhancing the transfer across the BBB, was capable of reducing amyloid burden in APP/PS1 transgenic mice." (PMID 37646225, 2024). "Recent studies have demonstrated the presence of APP, β- and γ- secretase in exosomes and at the endosomal level providing further evidence of a clear link between amyloid and EVs." (PMID 38943196, 2024). "Using microRNA to target the amyloidogenic pathway, the regulatory role of BACE1 and APP has been demonstrated in experimental models of AD utilizing mice that have been manipulated to accumulate amyloid in the brain as their primary pathology." (PMID 39459541, 2024). "In this study, we demonstrated that the deletion of mir‐33 significantly reduces amyloid pathology in an APP/PS1 mouse model." (PMID 39345217, 2024). "Previously, we found TfRMAb-TNFR to be protective in a mouse model of amyloidosis (APP/PS1) and tauopathy (PS19), and herein we investigated its effects in mice that combine both amyloidosis and tauopathy (3xTg-AD)." (PMID 38500108, 2024). "Injection of LPS into the brains of APP transgenic mice leads to the clearance of some pre-existing amyloid deposits." (PMID 38916729, 2024). "Ultrasound stimulation affects microglial polarization, reduces amyloid plaque load, and enhances levels of anti‐inflammatory factors in APP/PS1 mice." (PMID 39588954, 2024). "Our data showed an interesting sex-independent response whereby the male and female APP/PS1 mice had a marked endothelial dysfunction prior to the onset of amyloid pathology." (PMID 38862757, 2024). "It seems that the progression of the vascular dysfunction is marked with the aging of the female APP/PS1 mice as they exhibited an increased aortic stiffness compared to the female APP/PS1 mice prior to the onset of amyloid pathology." (PMID 38862757, 2024). "Amyloid plaques, composed of β-amyloid (Aβ) peptides derived from the amyloid precursor protein (APP) through sequential cleavage by β- and γ-secretase, play a significant role in neurodegeneration." (PMID 39281480, 2024). "Accumulation of amyloid plaques is done via interaction between amyloid precursor proteins (APP) and two proteases: beta (β-) and gamma (γ-) secretases." (PMID 38739937, 2024). "Since our prior observation of the AP-4 dystrophies carrying organelles enriched in APP processing machinery had motivated us to examine their contribution to amyloid plaque pathology, we next examined if these dystrophies persisted in the 5xFAD background." (PMID 39632089, 2024).
amyloid (continued). "Utilizing an APOE4‐centric mouse model of amyloidosis (APP/PS1/APOE4), we observed that humanin P3S significantly attenuated brain amyloid‐beta accumulation compared to the wild‐type humanin." (PMID 38520065, 2024). "A recent study has shown that B cell deficiency in different mouse models of AD (3xTgAD, APP/PS1, 5xFAD) leads to a decrease in amyloid deposits at the base of the hippocampus and improved cognitive function." (PMID 39404388, 2024). "Amyloid pathogenesis is initiated with abnormal cleavage of APP (integral plasma membrane protein) through β-secretases (BACE1) and γ-secretases." (PMID 39507054, 2024). "In an amyloid mouse model (APP/PS1), memory impairment and oxidative stress were attenuated with quetiapine." (PMID 39767797, 2024). "The expression of AHI1 promotes the intracellular translocation of APP and inhibits the amyloidosis process of APP, thereby decreasing the level of cellular Aβ in an in vitro model of AD." (PMID 38975245, 2024). "Overall, the study results indicate that GBE intervention can mitigate dendritic spine damage, alleviate amyloid pathology, and suppress neuronal apoptosis in the brains of APP/PS1 mice." (PMID 39238068, 2024). "MIC-M2 featured hub genes SORL1 and B2M, both implicated in a variety of AD-related processes such as trafficking of APP and resultant amyloidosis in AD." (PMID 38913039, 2024). "In our study, female APP/PS1 mice at 3 months of age had a decreased receptor-independent contraction to KCl prior to the onset of amyloid pathology." (PMID 38862757, 2024). "Our data show that prior to the onset of amyloid pathology, both male and female mice present with endothelial dysfunction, and as the disease progresses, both male and female APP/PS1 mice show resistance artery hypercontractility." (PMID 38862757, 2024). "Conversely, the selective expression of APOE3 in microglia in APP/PS1 mice provides sufficient protection against the development of amyloid pathology, whereas APOE4 microglia fail to do so." (PMID 39595034, 2024). "We used an APP knock-in mouse model, APPNL-G-F, exhibiting amyloid pathology, to study the association between AD brain pathology and protein changes in mouse ChP tissue and CSF using liquid chromatography mass spectrometry." (PMID 39020361, 2024). "Overall, these single cell transcriptomics data suggest that inflammasome activation is not a central regulator of microglial activation in the healthy brain or upon amyloid pathology in the APP/PS1 model." (PMID 38352874, 2024). "The pathological hallmark of AD, amyloid plaques derived from BACE1-cleaved APP, were significantly decreased in number and size of foci in the hippocampus and cortex of VIP@siBACE1-treated APP/PS1 mice." (PMID 38734698, 2024). "By focusing on the early effects of Aβ/APP-proteolytic products overproduction in mouse models of amyloidosis, we sought to disentangle elevated network activity and synaptic alterations." (PMID 39262788, 2024). "To conclude, this study used a mature-onset Tet-Off APP mouse model of amyloidosis, which resembles LOAD in humans, to uncover impairments in brain-fluid circulation at advanced stages of pathology." (PMID 36707887, 2023). "The Aβ is a highly hydrophobic peptide of 39–43 amino acids, released by the proteolytic cleavage of amyloid-β precursor protein (APP), which is hydrolyzed to Aβ via the amyloidosis pathway with a continuous enzymatic action of β- and γ- secretase." (PMID 36774494, 2023). "While APP/PS1 mice show significant amyloid deposits and loads, adoptive transfer of TCRAβ-Tregs reduced both soluble and insoluble fragments of Aβ in the cortex, whereas polyclonal Treg treatment slightly, but insignificantly, reduced Aβ deposition." (PMID 38111016, 2023). "Targeted deletion of Abca7 alleles affects brain lipid homeostasis and significantly increases cerebral amyloid burden in APP/PS1 amyloidosis model." (PMID 37986179, 2023).
amyloid (continued). "Amyloid plaques are formed by the accumulation of extracellular aggregates of β-amyloid (Aβ) peptides, resulting from the sequential proteolysis of the amyloid precursor protein (APP) by β and γ secretases." (PMID 37511507, 2023). "In this study, we tested the effects of early and chronic microglial p38α suppression on cognitive performance, neuroinflammatory processes, and amyloid pathology in WT and APP/PS1 AD model mice." (PMID 37256881, 2023). "In the cortex of 12-month-old APP-KI mice, Apoe was localized within amyloid plaques that were positive for the anti-Aβ antibody (82E1), and there was partial overlap between Apoe and these plaques." (PMID 37705104, 2023). "In the amyloidosis pathway, the β-secretase slits APP at the N-terminal of Aβ (Asp1β site), thereby releasing the N-terminal fragment of APP and 99 amino acids APP-CTF (C99 or CTFβ)." (PMID 37836528, 2023). "Collectively, the results show that cGP reduces amyloid pathology in two brain regions, i.e., the hippocampus and cortex of APP/PS1 mice." (PMID 36909366, 2023). "A mutation of the gene encoding amyloid precursor protein (APP) has emerged as a prominent candidate because of both the significant amyloid deposits in AD and the isolation of a fragment of APP, Aβ, from amyloid plaques." (PMID 37232860, 2023). "Here, we sought to assess the efficacy of the GS in a transgenic Tet-Off APP mouse model of amyloidosis, in which the expression of mutant APP was delayed until maturity, mimicking features of late-onset AD—the most common form of dementia in humans." (PMID 36707887, 2023). "Altogether, these results indicate that following four months of curative treatment with PEL24-199, the long- and short-term spatial memories were restored in this APP/PS1 transgenic model of amyloidosis." (PMID 36982363, 2023). "Despite this, we were still able to show that microelectrode implantation accelerates the onset of amyloid pathology even within 2 month-old APP/PS1 mice." (PMID 37531953, 2023). "The coverages of amyloid plaques and the ratio of GFAP coverage to amyloid plaque coverage were significantly higher in early- and advanced-stage APP/PS1 mice than in their age-matched WT littermates (p < 0.05 for both)." (PMID 37433857, 2023). "Our own works have shown that adoptive transfer of Aβ-reactive Teffs accelerate amyloid pathology and cognitive defects in mice expressing chimeric mouse/human amyloid precursor and a mutant human presenilin 1 protein (APP/PS1)." (PMID 38111016, 2023). "Restoration of SWA via astrocyte targeting reduces amyloid plaque deposition, restores the calcium homeostasis in neurons, and improves sleep-dependent memory consolidation in APP mice." (PMID 37567942, 2023). "Early in AD, extracellular amyloid β (Aβ) accumulates as amyloid-beta precursor protein (APP) is cleaved, and aggregates of Aβ molecules form amyloid plaques." (PMID 37937068, 2023). "Future studies using differential models (i.e., accelerated amyloidosis models, such as 5xFAD, or APP knock-in models), should address the existence of astrocytic alterations early in the development as a hallmark of AD." (PMID 37628778, 2023). "Recent studies suggest that BS-I induces sufficient innate immune stimulation and phagocytosis to promote amyloid clearance, thereby reducing amyloid plaque burden in APP/PS1 mice." (PMID 37445682, 2023). "It has been observed that the loss of TLR4 function results in blunted microglial activation and increased amyloid pathology in 9-month APP/PS1 mice, whilst younger (5-month) mice showed impaired microglial activation but no change in Aβ deposition." (PMID 37986179, 2023). "In this study, we examined the effects of cGP on spatial memory and amyloid plaque load in APP/PS1 double transgenic mouse model of AD." (PMID 36909366, 2023). "For example, apigenin (40 mg/kg) improved memory deficits in an amyloid-based transgenic mouse model of AD, the APP/PS1 mouse." (PMID 37446262, 2023).
amyloid (continued). "After observing that PE prevents the progressive increase in Aβ levels in plasma, we conducted further evaluations to assess the effect of PE on the progression of amyloid pathology in the brains of both treated and control APP/PS1 mice." (PMID 38069410, 2023). "At this age, APP/PS1 mice are just beginning to present amyloid deposition and therefore it is still relatively early in the progression of AD pathology typical for this mouse model." (PMID 37531953, 2023). "Transgenic mice expressing the mutations of familial-associated AD genes (APP/PS1/PS2) progressively developed brain Aβ plaques and memory deficits, reinforcing the relation between amyloid deposition and memory impairment." (PMID 37111540, 2023). "Blocking ACAT1/SOAT1 activity by genetic ablation or pharmacological inhibition has been shown to reduce amyloid pathology in mice by lowering levels of the amyloid precursor protein (APP) and its toxic product, Aβ." (PMID 36982602, 2023). "Although the impact of GA in the APP/PS1 model of amyloidosis has been reported multiple times, currently there is only one other study of GA use in 5xFAD mice." (PMID 37513996, 2023). "These diurnal oscillations in Aβ levels in brain ISF are dissipated and the sleep–wake cycle is disrupted after Aβ plaque formation in the APP/PS1 mouse model of amyloidosis." (PMID 36721148, 2023). "The identification of an IRE in the 5′UTR of the APP transcript led to a novel therapeutic approach aimed at reducing amyloidosis by several FDA-pre-approved drugs targeted to the IRE in the APP mRNA 5′UTR." (PMID 36899898, 2023). "An impaired cleavage of APP protein results in the generation and extracellular secretion of β-amyloid that will ultimately assemble to form amyloid plaques." (PMID 37784196, 2023). "8‐month‐old APP/PS1 mice presented with obvious amyloid plaque, which was alleviated by CTB treatment (p = 0.0367)." (PMID 37759382, 2023). "Another important finding reported by these studies was that eNOS knockout alone was not sufficient to induce tau pathology, as increased p-tau was only observed in eNOS knockout mice that also had amyloid pathology (i.e., APP/PS1/eNOS−/− mice)." (PMID 37238700, 2023). "APP mice overexpress a human mutant APP transgene and a human mutant PS1 variant, generate Aβ and deposit amyloid plaques starting at 4.5–5 months of age66." (PMID 37567942, 2023). "Adoptive transfer of either TCRAβ-Tregs or polyclonal Tregs to APP/PS1 mice reduced dense amyloid plaque deposition in both the cortex and hippocampus compared with untreated APP/PS1 mice." (PMID 38111016, 2023). "Surprisingly, robust IL-1β overexpression within the hippocampus of the APP/PS1 mouse model of AD led to a reduction in amyloid pathology." (PMID 37446262, 2023). "Blockade of the GSK3β pathway in APP transgenic mice resulted in a reduction in Aβ production and amyloid plaque load." (PMID 37432552, 2023). "BACE-1 has the substrate amyloid precursor protein (APP) and generates amyloid plaques in the brain, causing several amyloid-linked neurodegenerative diseases." (PMID 37397495, 2023). "This was despite 20-month-old APP/PS1 mice being at the height of amyloid accumulation and microglial activity." (PMID 38023614, 2023). "The importance of BDNF is further substantiated by the beneficial effects of physical exercise, which increases BDNF and TrkB expression, reduces APP processing and amyloid aggregation, and protects against cognitive decline in animal models and AD patients." (PMID 36397124, 2022). "To determine the functional contribution of circulating monocytes to amyloid plaque pathogenesis, we performed splenectomy on male APP/PS1mTmG;Flt3-Cre mice." (PMID 35511433, 2022). "In a follow-up study, 14 months old APP/PS1 mice were treated with liraglutide once daily for 8 weeks to test if the drug had effects in animals where the amyloid-related pathology already had been established." (PMID 35965783, 2022).
amyloid (continued). "To further understand how metabolic syndrome and amyloid pathology interact, we performed RNA-seq analysis of the brain samples of APP/PS1/Sirt3-/- mice." (PMID 36396721, 2022). "First, we characterized amyloid homeostasis and hippocampus-dependent memory in 4- to 5-month-old APP/PS1 (APPSwe/PS1ΔE9) mice." (PMID 35045289, 2022). "As Nmnat1 is a predominantly nuclear-localized enzyme, it is unlikely for Nmnat1 to directly interact with APP or amyloid plaques." (PMID 35401143, 2022). "In the double transgenic APP/PS1 model of amyloidosis, increased levels of CCL3 and CCL4 were found in the brain within a frame of 7 to 15 months of age." (PMID 35821178, 2022). "Our co-staining results confirm that amyloid plaques were closely surrounded by GFAP-positive astrocytes in the APP/PS1 brain." (PMID 35895177, 2022). "Tg4510 (a model of tau deposition) and APP/PS1 (a model of amyloid deposition) mice fed a KD for 3 months performed significantly better on the motor tests, compared to those fed a normal diet, although this was not the case in cognitive tests." (PMID 35855338, 2022). "The Aβ peptides are a key component of amyloid plaques which are derivatives of APP proteolytic cleavage; therefore, it is suggested that Aβ and APP are contributing factors to the pathogenesis of AD." (PMID 35163117, 2022). "Amyloid plaques or aggregates are composed of Aβ peptide, which is derived from the abnormal processing of amyloid precursor protein (APP) in the brain." (PMID 36552006, 2022). "In the amyloidosis route, Aβ1-42 is generated when APP is sequentially cleaved by β and γ secretases; however, in the non-amyloid pathway, APP is cleaved by α and γ secretases, which avoids Aβ production and seems to be a protective process." (PMID 36159454, 2022). "A major finding from our present study was the regulation of APP trafficking by gamma frequency light flicker in these two transgenic mouse models of amyloidosis." (PMID 35199454, 2022). "Authors demonstrated in a transgenic model of amyloidosis, mice APP/PS1, that impaired microglial phagocytosis results in the development of fewer dense-core plaques." (PMID 36613460, 2022). "Mutations in these genes lead to pathogenic processing of APP to increase expression of Aβ 42, a 42-residue-long fragment of APP which aggregates into Amyloid plaques in the brains of AD patients." (PMID 36275000, 2022). "The overall result of Congo Red staining of APP/PS1 mouse hippocampus sections revealed the limited effect of 3-month THC treatment on reducing the amyloid deposits in the hippocampi." (PMID 35269905, 2022). "In a chronic study testing liraglutide, APP/PS1 mice were treated for 8 months starting at 2 months of age before the amyloid pathology developed." (PMID 35965783, 2022). "In summary, our findings revealed that DS-related USP25 plays a role in AD-related amyloid pathology by modulating APP processing and degradation, providing a potential pharmacologic target for treating AD, especially in patients with DS." (PMID 35229730, 2022). "Transgenic mouse models of Alzheimer’s disease (AD) overexpress mutations of the human amyloid protein precursor (APP) and presenilin-1 (PSEN1) genes, which are known causes of amyloid pathology in familial AD." (PMID 35163801, 2022). "Thus, early-onset familial AD is caused by mutations in the substrate for Aβ production (APP) or the proteases (presenilins) performing its release, and all these mutations enhance the aggregation propensity of Aβ and thus drive AD via increased amyloid pathology." (PMID 35862308, 2022). "To understand how Bmal1-depleted astrocytes behave in the context of Aβ pathology, we examined astrocyte activation in the cortex of BMAL1 aKO mice crossed to the APP/PS1-21 model of Aβ-amyloidosis (Aldh1l1-CreERT2;Bmal1fl/fl;APP/PS1-21)." (PMID 35110643, 2022).